USP44 (ubiquitin specific peptidase 44)
Description:
Deubiquitinase that plays a key regulatory role in the spindle assembly checkpoint or mitotic checkpoint by preventing premature anaphase onset. Acts by specifically mediating deubiquitination of CDC20, a negative regulator of the anaphase promoting complex/cyclosome (APC/C). Deubiquitination of CDC20 leads to stabilize the MAD2L1-CDC20-APC/C ternary complex (also named mitotic checkpoint complex), thereby preventing premature activation of the APC/C. Promotes association of MAD2L1 with CDC20 and reinforces the spindle assembly checkpoint. Also promotes the deubiquitination of histone H2A and H2B. Recruited to RNF8/RNF168-ubiquitinated chromatin surrounding double stranded breaks (DSBs), promotes hydrolysis of such ubiquitin conjugates, thus negatively regulating protein recruitment to damaged chromatin. Participates in nucleotide excision repair (NER) pathway by deubiquitinating DDB2 to prevent its premature degradation so it can remain on damaged chromatin (By similarity). Promotes FOXP3 stabilization through 'Lys-48'-linked deubiquitination leading to increased stability and increased regulatory T-cell lineage stability. Also plays a positive role in innate immune response to DNA viruses by deubiquitinating STING1, selectively removing its 'Lys-48'-linked polyubiquitin chains and stabilizing it.
Synonyms: FLJ14528
Tractability: PROTAC: UniProt records ubiquitination sites on it; ubiquitination databases record sites on it.
Gene: Protein-coding gene on chromosome 12 (95,516,560 to 95,553,341, reverse strand). Ensembl gene ENSG00000136014.
Subcellular location: Nucleus; Cytoplasm
Subcellular location (Human Protein Atlas): Microtubules; Nucleoli fibrillar center
Pathways (Reactome):
Metabolism of proteins: Ub-specific processing proteases
Gene Ontology:
Molecular function: cysteine-type deubiquitinase activity; deubiquitinase activity; protein binding; zinc ion binding
Biological process: antiviral innate immune response; negative regulation of mitotic metaphase/anaphase transition; negative regulation of ubiquitin protein ligase activity; protein deubiquitination; regulatory T cell differentiation; nucleotide-excision repair; proteasome-mediated ubiquitin-dependent protein catabolic process; regulation of cell cycle process; regulation of mitotic cell cycle spindle assembly checkpoint; chromosome segregation
Cellular component: fibrillar center; nucleus; chromatin; cytoplasm; mitotic spindle; nucleoplasm
Genetic constraint (gnomAD): Loss-of-function variants: 57 observed, 68.76 expected, observed/expected ratio (o/e) 0.83, 90% interval 0.67 to 1.03. The upper end of that interval is the gene's LOEUF score, 1.03, which puts it in group 4 of 6, group 1 being the genes least tolerant of losing a copy. Missense variants: 741 observed, 878.68 expected, observed/expected ratio (o/e) 0.84, 90% interval 0.79 to 0.9. Synonymous variants: 296 observed, 309.01 expected, observed/expected ratio (o/e) 0.96, 90% interval 0.87 to 1.05.
Gene-disease validity (ClinGen):
ClinGen rates the evidence that USP44 causes each of these diseases.
congenital heart disease (autosomal dominant): Limited. A heart disease that is present at birth.
Homologues: Orthologues: chimpanzee USP44 (99% identical), macaque USP44 (95% identical), pig USP44 (91% identical), dog USP44 (90% identical), rabbit USP44 (87% identical), rat Usp44 (81% identical), mouse Usp44 (80% identical), tropical clawed frog usp44 (71% identical), zebrafish usp44 (64% identical), guinea pig USP44 (54% identical). Paralogues in human: USP49 (58% identical), USP3 (26% identical), USP20 (25% identical), USP33 (24% identical), USP32 (19% identical), USP19 (19% identical), USP4 (18% identical), USP51 (18% identical), USP30 (18% identical), USP15 (17% identical), USP16 (17% identical), USP2 (17% identical), and 59 more.
Diseases named in the same sentence as USP44 in open-access papers:
USP44 is named in the same sentence as 58 diseases in open-access papers, as found by Europe PMC text mining. Sharing a sentence is not in itself a finding about the gene and the disease. The quoted sentences say what the papers report.
glioma (11 papers, 2020 to 2025). A benign or malignant brain and spinal cord tumor that arises from glial cells (astrocytes, oligodendrocytes, ependymal cells). "Additionally, USP44 was shown to be important for breast cancer cell line growth in vitro, and in other studies, USP44 over‐expression was reported in high grade gliomas and linked to poor outcomes." (PMID 32644293, 2020). "Further, Linc-RA1 represses autophagy and improves radioresistance by avoiding H2Bub1/ ubiquitin specific peptidase 44 (USP44) combination in glioma cells." (PMID 35156508, 2022). "For the functions of these genes, USP44 is related to proliferation, migration and invasion, induced apoptosis, and arrested cell cycle in the G2/M phase in the established glioma cell lines." (PMID 32633782, 2020). "In current study, overexpression of USP44 enhanced the malignancy of glioma by stabilizing tumor-promoter securing." (PMID 32164618, 2020). "In glioma, USP44 promotes proliferation, migration and invasion while suppressing apoptosis in glioma cells." (PMID 32285989, 2020). "USP44 expression level is significantly upregulated in glioma and gastric cancer, whereas it's downregulated in lung cancer and colorectal adenomas." (PMID 32285989, 2020). "Mechanistically, linc-RA1 stabilizes H2Bub1 levels by inhibiting its binding with USP44, thereby inhibiting autophagy activation and contributing to glioma cell radioresistance." (PMID 32934196, 2020). "However, Zou and colleagues showed that USP44 overexpression promotes the malignancy of glioma." (PMID 32164618, 2020). "Within this enzyme class, ubiquitin-specific protease 44 (USP44) has been found to be dysregulated in cancers such as colon cancer, leukemia, and glioma." (PMID 37204480, 2023). "Their findings revealed that Linc-RA1 inhibited the interaction between ubiquitin-specific protease 44 (USP44) and H2B K120 monoubiquitination (H2Bub1), which consequently inhibits autophagy and promotes radioresistance in glioma cells." (PMID 33525678, 2021). "In glioma, Linc-RA1 can combine with H2B to stabilize the level of H2B K120 monoubiquitination and inhibit the interaction between H2Bub1 and ubiquitin-specific protease 44 (USP44), thus regulating autophagy and enhanced radioresistance." (PMID 35600868, 2022). "Mechanistically, linc-RA1 stabilized the level of H2B K120 monoubiquitination (H2Bub1) by combining with H2B and inhibiting the interaction between H2Bub1 and ubiquitin-specific protease 44 (USP44), which inhibited autophagy, thus contributing to glioma radioresistance." (PMID 32934196, 2020).
colorectal cancer (9 papers, 2017 to 2024). A primary or metastatic malignant neoplasm that affects the colon or rectum. "In a methylation-specific curve biopsy analysis, USP44, encoded by a gene on chromosome 12, was identified as a possible DNA methylation signature contributing to the early detection of colorectal cancer associated with IBD." (PMID 35145062, 2022). "Previous studies have indicated that USP44 functions as a tumor suppressor in hepatocellular carcinoma, pancreatic cancer, colorectal cancer, renal clear cell carcinoma and non‐small lung cancer 38, 40, 42-44." (PMID 39430240, 2024). "USP44 was also reported to inhibit cell proliferation in colorectal cancer, clear cell renal cell carcinoma, and non–small cell lung cancer." (PMID 37204480, 2023). "Still other studies suggest that USP44 is widely down‐regulated in other human cancer types (e.g., colorectal cancer), and a role for USP44 as a tumor suppressor has also been described in pancreatic cancer." (PMID 32644293, 2020). "In recent years, studies have shown that the expression of USP44 in a variety of tumors has been significantly reduced, including colorectal cancer, breast cancer, esophageal cancer, glioblastoma, renal cancer and testicular cancer." (PMID 32266120, 2020). "However, the correlation between USP44 methylation and IBD-associated colorectal cancer was only detected in IBD patients with associated neoplasia, and not in patients with sporadic colorectal cancer." (PMID 35145062, 2022).
prostate carcinoma (8 papers, 2020 to 2025). A carcinoma that arises from epithelial cells of the prostate gland. "However, contradictory findings have been reported in gastric and prostate carcinomas, in which USP44 upregulation was associated with promotion of cancer progression and tumorigenesis, suggesting that USP44 has various roles in various cancer types." (PMID 37204480, 2023). "We further evaluated for the first time the clinical significance of the detection of USP44 methylation in plasma cell-free DNA of prostate cancer patients and we report a statistically significant association between USP44 promoter methylation and overall survival." (PMID 34572834, 2021). "In 2017, Dora Londra and colleagues discovered the feasibility of predicting prostate cancer prognosis by detecting the methylation level of the USP44 promoter in serum." (PMID 40936898, 2025). "We evaluated for the first time the prognostic significance of USP44 promoter methylation in plasma cfDNA from patients with prostate cancer." (PMID 34572834, 2021). "In this study, we examined for the first time USP44 promoter methylation in plasma cell-free DNA (cfDNA) of patients with prostate cancer (early stage n = 32, metastatic n = 39) and 10 healthy donors (HD)." (PMID 34572834, 2021). "So far, there is only one study on USP44 in prostate cancer, based on the protein expression of this gene by immunofluorescence." (PMID 34572834, 2021). "We then examined the methylation status of USP44 in plasma cfDNA samples from 39 prostate cancer patients with verified metastasis." (PMID 34572834, 2021). "In vitro experiments performed in this study suggested that the loss of USP44 reduced both the EZH2 protein levels and oncogenic activity of prostate cancer cells." (PMID 34572834, 2021). "On the contrary, in the metastatic setting, a high percentage (51.4%) of plasma cfDNA samples was positive for USP44 promoter methylation, indicating that USP44 promoter methylation may play an important role in this stage of prostate cancer." (PMID 34572834, 2021). "However, further studies are needed to clarify the differences in thephysiological function and mechanisms of USP7 and USP44 as EZH2 protein stabilizersin prostate cancer." (PMID 32453339, 2020). "USP44 can induce the genesis of prostate cancer cells partly by stabilizing EZH2." (PMID 32164618, 2020). "In contrast, knockdown of USP44 in prostate cancer cells reduced tumorigenesis." (PMID 32644293, 2020). "Recently,we reported the deubiquitinating activity of USP44 and the subsequent stabilizationof EZH2 protein in prostate cancer cells (Parket al., 2019)." (PMID 32453339, 2020). "In their study, the researchers applied real-time methylation-specific PCR technology and found no detection of USP44 promoter methylation in the serum of healthy individuals (n=10) and early-stage prostate cancer patients (n=32)." (PMID 40936898, 2025). "We then examined the methylation status of USP44 in plasma samples from 32 early prostate cancer patients; we did not observe methylation of USP44 in this group (0%)." (PMID 34572834, 2021). "We previously reported the deubiquitinatingactivity of USP44 and subsequent EZH2 protein stabilization in prostate cancer cellsand suggested that targeting USP44 might be an efficient anticancer strategy forEZH2-dependent cancers irrespective of the enzymatic activity of EZH2." (PMID 32453339, 2020).
breast carcinoma (7 papers, 2018 to 2024). "In vitro experiments in breast cancer and TCGA analysis suggested that USP44 low expression was caused by promoter hypermethylation." (PMID 34572834, 2021). "USP44 is another deubiquitinase modulating H2Bub1, which suppresses or promotes breast cancer growth determined by the particular subtypes of breast cancer." (PMID 34575114, 2021). "Experiments in breast cancer cell lines revealed that USP44 hypermethylation promotes cell proliferation and metastasis." (PMID 34572834, 2021). "USP44 methylation is reported so far in a small number of studies in breast cancer, colorectal neoplasia, and non-small cell lung cancer." (PMID 34572834, 2021). "As a biomarker of breast cancer stem cells, USP44 interacts directly with the WD40 motif‐containing proteins, such as the N‐CoR component, TBL1XR1, which is highly expressed in breast cancer cells." (PMID 32394588, 2020). "RNA-sequencing (RNA-Seq) transcriptome data and DNA methylation data of the TCGA-BRCA revealed that USP44 methylation could be potential biomarker of breast cancer." (PMID 34572834, 2021). "Moreover, breast cancer stem cells with high levels of the ubiquitin-specific protease 44 (USP44) display centrosome amplification and increased IL-8 expression, which promotes vascularization and predicts aggressive behavior." (PMID 30458137, 2018). "We used the TCGA database to analyze the expression of USP family members, and found that USP2, USP6, USP44 and USP53 in breast cancer tissues were significantly down-regulated compared with those in normal breast tissues, among which the first three have been studied in this field." (PMID 39044157, 2024). "Analysis of TCGA data in breast cancer has shown that USP44 expression was significantly decreased when compared to normal." (PMID 34572834, 2021).
gastric cancer (7 papers, 2017 to 2024). A primary or metastatic malignant neoplasm involving the stomach. "Our data suggest that aneuploidy caused by USP44 overexpression promotes tumor progression in gastric cancer." (PMID 28544703, 2017). "USP44 is associated with DNA aneuploidy and can predict outcomes in gastric cancer." (PMID 39605891, 2024). "The two transcripts are involved in a tumor-promoting regulatory axis in the case of gastric cancer involving USP44, confirming the solid binding interaction." (PMID 36982797, 2023). "On the other hand, Foxo3 is elevated in gastric cancer (GC) cells and promotes GC malignancy in vitro and in vivo by enhancing USP44 expression via targeting miR-143-3p." (PMID 34555810, 2021). "DNA aneuploidy was observed in 124 gastric cancer cases and high USP44 expression in cancer strongly correlated with DNA aneuploidy (P = 0.0005)." (PMID 28544703, 2017). "We evaluated the proportion of USP44‐positive nuclei in clinical specimens of gastric cancer and normal mucosa by immunohistochemical staining and found that USP44 expression was significantly higher in gastric cancer than normal mucosa." (PMID 28544703, 2017). "In this study, we examined the relationship between USP44 overexpression and DNA aneuploidy using clinical specimens of gastric cancer and provide the first evidence for the prognostic significance of evaluating USP44 expression combined with DNA aneuploidy." (PMID 28544703, 2017). "While we did not observe a significant correlation between clinicopathological features and USP44 expression, we found that high USP44 expression strongly correlated with DNA aneuploidy in gastric cancer (P < 0.001)." (PMID 28544703, 2017). "We next investigated USP44 expression by immunohistochemistry in the 207 gastric cancer samples as described in Materials and Methods." (PMID 28544703, 2017). "Results from the multivariate analyses showed that USP44 was an independent poor prognostic factor of PFS for all gastric cancer patients." (PMID 28544703, 2017). "We analyzed USP44 expression in 207 patients with gastric cancer by immunohistochemistry and found that the proportion of USP44 expression was higher in gastric cancer tumors (mean, 39.6%) than in gastric normal mucosa (mean, 14.6%) (P < 0.0001)." (PMID 28544703, 2017). "We also found that high USP44 expression was an independent poor prognostic factor for gastric cancer with DNA aneuploidy." (PMID 28544703, 2017). "Although USP44 has been reported as a prognostic indicator in lung cancer, gastric cancer and breast cancer, its prognostic value in NPC remains unknown." (PMID 35079021, 2022). "In addition, USP44 is regulated by the circFOXO3/miR-143-3p axis in GC, in which circFOXO3 functions as a miR-143-3p sponge to promote USP44-directed malignancy in gastric carcinoma." (PMID 36497313, 2022). "While aneuploidy was not shown to be a prognostic factor in gastric cancer, our findings showed that the high‐USP44 expression group was associated with a poorer prognosis than the low expression group." (PMID 28544703, 2017). "In summary, here we report that the combination of USP44 expression and DNA ploidy status might serve as an independent prognostic marker in gastric cancer." (PMID 28544703, 2017). "Together our results show that USP44 overexpression induces DNA aneuploidy in gastric cancer." (PMID 28544703, 2017). "Furthermore, we confirmed a significant correlation of high USP44 expression and DNA aneuploidy in gastric cancer." (PMID 28544703, 2017). "Collectively, our data show USP44 has clinical impact on the induction of DNA aneuploidy and poor prognosis in the CIN gastric cancer subtype." (PMID 28544703, 2017). "Aberrant expression of USP44 leads CIN in cells; however, the correlation between USP44 and DNA aneuploidy in gastric cancer is largely unknown." (PMID 28544703, 2017).
gastric cancer (continued). "In this study, we found that USP44 expression was higher in gastric cancer than in gastric normal mucosa and showed that USP44 overexpression related to DNA aneuploidy in gastric cancer." (PMID 28544703, 2017). "USP44 likely has novel functions that have not yet been discovered; overexpression of these unknown functions may also affect tumor invasion or pro‐metastasis activities in gastric cancer." (PMID 28544703, 2017). "In subgroup analyses, high USP44 expression was an independent poor prognostic factor of PFS and OS in aneuploidy gastric cancer, but not in diploidy cases." (PMID 28544703, 2017).
lung cancer (7 papers, 2017 to 2023). A malignant neoplasm involving the lung. "USP44 is also frequently downregulated in human lung cancers and its decreased expression is associated with a poor prognosis." (PMID 29088828, 2017). "Meanwhile, USP44 is frequently downregulated in lung cancer, leading to a poor prognosis, which is further corroborated in mice." (PMID 35281055, 2022). "In the study of lung cancer, the decrease of USP44 expression level improves the invasive ability of tumor cells and reduces the overall survival rate of patients." (PMID 32266120, 2020). "Another peak of homozygous deletions targeted the ubiquitin-specific protease USP44, specifically in lung cancer." (PMID 29089486, 2017). "As such, USP44‐deficient mice are more susceptible to the spontaneous development of tumors (particularly lung adenomas) than wild‐type mice when examined at 15 months of age—a finding in line with an observed link between low USP44 expression levels and poor outcomes in lung cancer." (PMID 32644293, 2020).
clear cell renal cell carcinoma (5 papers, 2020 to 2024). "A recent study demonstrated that USP44 overexpression inhibited the proliferation and migration of clear cell renal cell carcinoma cell lines; inversely, USP44 knockdown exerted opposite effects." (PMID 37609036, 2023).
pancreatic cancer (5 papers, 2020 to 2026). "Another study indicated that METTL3-mediated m6A methylation decreased the expression of lncRNA DBH-AS1 in pancreatic cancer, while DBH-AS1 increased the sensitivity of pancreatic cancer cells to gemcitabine through the miR-3163/USP44 axis." (PMID 37264402, 2023).